PDK1 (pyruvate dehydrogenase kinase 1)
Diseases named in the same sentence as PDK1 in open-access papers (continued):
Sharing a sentence is not in itself a finding about the gene and the disease.
tumor (continued). "Conversely, HIF-1α blocks the entry of pyruvate into the TCA cycle by upregulating pyruvate dehydrogenase kinase 1 (PDK1), driving tumor cell energy to glycolysis." (PMID 32257942, 2020). "This drug has been reported to have anti-cancer activity and mediates anti-tumor effects via the inhibition of PDK1." (PMID 33396819, 2020). "Proteins secreted by CAFs and omental tissues, such as IL-8, in the tumor microenvironment appeared to contribute to PDK1 upregulation and its metastasis functions." (PMID 32071289, 2020). "In conclusion, our experiments demonstrate that changes in metabolism by the inhibition of PDK1 affect mitochondrial quality control in tumor cells." (PMID 31949499, 2020). "In recent years, PDK1 has been the focus of many studies aimed at blocking glucose metabolism in tumor cells." (PMID 33396270, 2020). "Dichloroacetate (DCA), a PDK1 inhibitor, reverses the metabolic phenotype of tumor cells, shifting the metabolic flux to mitochondrial oxidative phosphorylation, which induces selective cytotoxicity 24-26." (PMID 31949499, 2020). "In this study, the relationship between PDK1-induced altered glucose metabolism and mitochondrial quality control was investigated by studying PDK1 as an entry point in tumor cells." (PMID 31949499, 2020). "PKCs are activated by the PI3K and PDK1 pathways and then regulate several genes involved in tumor progression, metastasis, and tumorigenesis, resulting in the promotion of tumor growth and metastasis." (PMID 32466580, 2020). "We intend to explore the function of miR-4290/PDK1 axis in cisplatin resistance using the tumor-bearing models of GC." (PMID 32321153, 2020). "For example, PI3K has been found to promote AKT and PDK-1 and eventually activate elF4B and S6 translation, thus inducing tumor cell proliferation and survival." (PMID 32818022, 2020). "While PDK4 and PDK2 are expressed at lower levels, PDK1 and PDK3 are supposedly overexpressed in PCa and associated with advanced tumor stages." (PMID 33384955, 2020). "More importantly, PDK1 is a direct target of miR-379, which functions as a tumor-inhibiting miRNA by targeting PDK1 in OS." (PMID 32039832, 2020). "Tyrosine phosphorylation activates PDK1 to promote the Warburg effect and in vivo tumor growth in leukemia and lung cancer cells." (PMID 32071289, 2020). "PDK1 can promote lactate production in tumor cells by increasing glycolysis and making the microenvironment acidic, which increases the invasive behavior of malignant cells." (PMID 32487245, 2020). "A xenograft tumour mouse model was used to determine the effect of pharmacological inhibition of PDK1 on PDAC cells growth in vivo." (PMID 31088502, 2019). "Treatment of mice with MP7 significantly inhibited tumour growth in vivo, indicating that targeting PDK1 pharmacologically is able to reduce PDAC progression in vivo." (PMID 31088502, 2019). "In a mouse model of OSCC, HOXA11-AS overexpression promoted tumor growth, concomitant with reduced miR-518a-3p expression and increased PDK1 expression." (PMID 31139017, 2019). "The expression of PDK1 was considered to correlate with a variety of tumor progression markers and with patient prognosis." (PMID 31506552, 2019). "The regulation of miR-518a-3p and PDK1 by HOXA11-AS is a mechanism of the tumor-promoting role of HOXA11-AS." (PMID 31139017, 2019). "PDK1/PDH regulates the key switch between glycolysis and oxidative phosphorylation in cancer cells, therefore, PDK1 is a crucial target for tumor metabolism in anticancer therapy." (PMID 30993888, 2019). "Such regulatory role of PDK1 is advantageous to tumor growth because it avoids the accumulation of ROS by reducing mitochondrial oxygen consumption." (PMID 29662084, 2018).
tumor (continued). "Using mouse xenograft models, PDK1 is found to be highly expressed in tumor hypoxic regions and promotes glycolysis to maintain stemness." (PMID 29106390, 2018). "In mouse xenograft tumor, PDK1 is accumulated in hypoxic regions and activates glycolysis to promote stem-like traits." (PMID 29106390, 2018). "Combining PI3K/mTOR inhibitors with AKT or PDK1 inhibitors suppressed this rephosphorylation, induced apoptosis, decreased colony formation, cell viability and growth of tumor xenografts." (PMID 29357370, 2018). "Dose reduction indices (DRI) for NVP-BEZ235 were greater than 1, indicating that a comparable anti-tumor effect requires lower concentrations of NVP-BEZ235 when combined with either PDK1 or AKT inhibitors." (PMID 29357370, 2018). "Accordingly, we suggest that in QM-PDAC and C-PDAC tumours, the upregulation of PDK1 and LDHA would likely favour the conversion of glucose-derived pyruvate to lactate, thereby promoting the Warburg effect in these PDAC subtypes." (PMID 30018740, 2018). "The immunofluorescence staining on xenograft tumors showed that PDK1 accumulated predominantly in tumor central regions, indicating that the function of PDK1 is related to hypoxia." (PMID 29106390, 2018). "The results showed that the mice inoculated with shPDK1 cells evidently formed smaller tumor masses than the mice injected with NTC cells, indicating that PDK1 is critical for tumor growth in vivo." (PMID 29106390, 2018). "Among all synthesized structures, TZ55.7, which was retained as a possible PDK1 (phospholipid-dependent kinase 1) inhibitor, exhibited the most significant cytotoxic activity against HT-29 tumor cell line." (PMID 30234098, 2018). "The same compound alongside compound TZ53.7, decreased PDK1 expression, in the HT-29 tumor cell line, in a dose dependent manner." (PMID 30234098, 2018). "Phosphorylated, active AKT is recruited to mitochondria under hypoxic conditions, whereby PDK1 is phosphorylated at T346, which switches tumor metabolism to glycolysis and maintains the redox balance needed for tumor cell survival and proliferation." (PMID 29562667, 2018). "The mice injected with H19 cells formed apparently larger tumor masses than the mice injected with Ctrl cells, but shPDK1 markedly reversed the tumor volumes, indicating PDK1 was critical for H19-mediated tumor growth." (PMID 29106390, 2018). "Compound TZ55.7, which was retained as a possible PDK1 inhibitor, exhibited the most significant cytotoxic activity against the HT-29 tumor cell line (IC50 = 87.95 μM)." (PMID 30234098, 2018). "In this assay, MDA-MB-231 cells were injected subcutaneously in nude mice, and frozen sections of the tumor xenografts were immunofluorescence stained for PDK1 expression." (PMID 29106390, 2018). "PDK1 activation of PKC also contributes to increased cell survival in some tumor types, likely by interacting with Bcl2-family proteins." (PMID 29093665, 2017). "There was significantly stronger expression of PDK1 in the hypoxic zones of the peritheliomatous arrangement of the tumor cells and vitreous seeds." (PMID 28505181, 2017). "The expression of PDK1 mRNA varied significantly in different tumor samples, ranging from 1.6 to 11 fold compared to control retina." (PMID 28505181, 2017). "PDK1 mRNA was significantly overexpressed in RB tumor samples as well as Y79 and Weri-Rb1 cells compared to normal retinal tissue." (PMID 28505181, 2017). "Only one healthy specimen and less than half of the benign ones exhibited weak PDK1 expression, whereas all malignant as well as borderline tumours were stained positively." (PMID 29064423, 2017). "Careful investigation has identified multiple ways by which PDK1 regulates cell migration and tumor growth and invasion." (PMID 28287465, 2017). "Mouse GBM xenografts tumor cells exhibited heterogeneous labeling of PDK1/EGFRvIII, with positive areas of staining detected alongside negative ones and the DCA treated tumors showed with very low PDK1/EGFRvIII." (PMID 28410193, 2017).
tumor (continued). "Experiments showed that, as a result of dnLEF‐1 expression, PDK1 activity was reduced, Warburg metabolism was diminished, and tumor mass was reduced approximately four‐ to fivefold." (PMID 28183841, 2017). "In recent years PDK1 has been an emerging target of importance in pathogenesis of various tumor types." (PMID 27551332, 2016). "Additional research is required, and more connections between apoptosis and tumor metabolism must be identified before PDK1 inhibition can be used in a clinical setting." (PMID 26593251, 2016). "These are also the prominent, tumor promoting features acquired by OVCAR3 cells after introduction of sfRon, which is associated with strong activation of PDK1 pathway in these cells." (PMID 27551332, 2016). "PKCα is another trafficking molecule of PDK1, which is a key regulator of cell growth and differentiation and its activation is believed to promote tumor progression." (PMID 27494022, 2016). "AR-12 was originally proposed to exhibit anti-tumor activity through inhibition of the enzyme PDK-1 within the PI3K pathway, a mechanism which we largely disproved in 2005 and 2006." (PMID 26887051, 2016). "This upregulation at the gene level corresponded to sustained higher levels of p-PDH at the protein level, suggestive of enhanced PDK1 activity in tumor cells interacting with adipocytes." (PMID 27588494, 2016). "Pharmacological inhibition of PI3Kα resulted in a modest delay in tumor growth in shGFP control xenografts but was sufficient to induce durable tumor shrinkage in tumors with ablated PDK1." (PMID 27451907, 2016). "For example, an increase in PDK1 levels by exogenous PDK1 expression in the cells suppressed colony formation and tumor growth, similar to the effects of RNF126 depletion." (PMID 27462466, 2016). "Although the drug-targeted proteins ER/PR and interesting mTOR/GSK3/TS2/PDK1/ER_P118 cluster had shown the consistent patterns between cells and tumor, low protein-based correlations were observed between cells and tumors." (PMID 27556158, 2016). "PDK1 inhibition has been shown to have powerful and broad spectrum anti-tumor effects in vitro, and these effects are relatively unique compared to tyrosinase inhibitors." (PMID 26593251, 2016). "In tumor cells, PDK1 acts as a brake blocking the CBL-b E3 ligase, thereby preventing the degradation of key oncoproteins, such as PI3K and BCL-xL, by proteasome." (PMID 26593251, 2016). "PDK1 not only acts as a metabolic enzyme but also as an oncogene protecting tumor cells from apoptosis." (PMID 26593251, 2016). "miR-375 functions via targeting multiple genes involved in tumor development, including Yap, PDK1, 14–3-3-ζ and SHOX2." (PMID 25762642, 2015). "This anti-tumor effect was associated with downregulation of HIF-1α, PDK1 and c-Myc, and a reduction in the number of tumor vessels." (PMID 26398947, 2015). "In both DZ and AS xenografts, PDK1 expression was observed in the nuclei and cytoplasm of the tumor cells." (PMID 26398947, 2015). "As an upstream regulator of AKT, PDK1 signaling is thought to play a key role in cancer cell growth, survival and tumor angiogenesis." (PMID 26684827, 2015). "Consistent with our findings, miR-375, known as a tumor suppressive gene, was reported to target PDK1, leading to the inhibition of PDK1/AKT/MTOR pathway and thus promotion of autophagy." (PMID 25333253, 2014). "Given the importance of PDK-1/Akt signaling in tumor growth, these compounds represent promising leads that can be exploited for the development of safer and more efficacious derivatives." (PMID 23875171, 2013). "Polycystin-1 is involved in cell adhesion and has been shown to inhibit cancer cell migration and invasion, leading to the suggestion that Pdk1 is a tumor suppressor gene." (PMID 24148528, 2013).
tumor (continued). "Although these findings do not provide a definitive target, it can be postulated that celecoxib, through its direct inhibition of PDK-1, and sulindac, via its interaction with RXRα, are able to downregulate Akt-dependent tumor cell invasion." (PMID 23875171, 2013). "In many tumors, particularly with PTEN deletions, the PI3K/PDK-1/Akt pathway is constitutively activated promoting tumor growth." (PMID 23875171, 2013). "A qPCR analysis of miR-375 and PDK1 was performed in 44 pairs of PC tumor and matched adjacent non-tumor tissues." (PMID 24137444, 2013). "The results show that miR-375 was significantly down-regulated in the PC tumor tissues, while PDK1 was upregulated in the PC tumor tissues." (PMID 24137444, 2013). "Our c4 tumours had lower expression of PDK1, lower ATP and slower growth rate compared to WT tumours; all of these observations would be consistent with the results of Dang." (PMID 21612605, 2011). "We have further shown that SDC-1 plays a key role in the anti-tumor properties of n-3 PUFA through induction of apoptosis via inhibition of the PDK-1-Akt-Bad signaling pathway." (PMID 21655218, 2011). "The present study has examined the effect of PDK1 transgene expression on mammary carcinogenesis, and how it impacts the tumor promoting effects of PPARδ activation." (PMID 21297860, 2011). "2-O-Bn-InsP5 specifically inhibits 3-phosphoinositide-dependent protein kinase 1 (PDK1) in vitro (IC50 in the low nanomolar range) and the PDK1-dependent phosphorylation of Akt in cell lines and excised tumours." (PMID 20051961, 2010). "GW501516 also elicited strong pS473Akt and pT308Akt staining in basal cells and in the submucosal layer, as well as in tumor and stromal tissue, which correlated with more intense PDK1 expression." (PMID 21318167, 2010). "Reducing the levels of PDK1 in PTEN+/− mice strongly protects them from developing a wide range of tumours." (PMID 20051961, 2010). "Using the Spearman's rank correlation for the percentage of tumour cells with positive immunoreactivity, there was a positive correlation between tumours expressing PDK-1 and PDH (r=0.57, P=0.03)." (PMID 18542064, 2008). "In many tumour cells, especially in those with deleted PTEN, the PI3K/PDK1/Akt axis is chronically activated and contributes to tumour growth and chemoresistance." (PMID 17955049, 2007). "Based on the key role of PDK1 in tumour growth, such streamlined compounds are expected to be useful in cancer therapy." (PMID 17955049, 2007). "Moreover, B4GALNT4 knockdown suppresses tumor growth in xenograft models and correlates with decreased PDK1 and p-AKT levels in vivo." (PMID 41698153, 2026). "In addition, GLIPR1 has been implicated in the regulation of epithelial–mesenchymal transition (EMT), cancer cell motility, and anti-tumor immune responses through pathways such as PI3K/PDK1/ROCK1." (PMID 41208460, 2025). "For tumor cells, this means that inhibition of PDK1 can hinder the progression of the cell cycle, leading to slowed or stagnant tumor cell proliferation, thereby preventing its excessive proliferation and exhibiting potential anti-tumor effects." (PMID 40971960, 2025). "In addition, the expression levels of HK2, LDHA, Glut1, and PDK1 were significantly decreased in the tumor tissues of MKN45R and HGC27R cells in the sh-SLC7A5 group." (PMID 40133832, 2025). "We believe potent PDK1‐PROTACs could contribute to tumor therapy and immunotherapy by glycolysis inhibition, which drives innovation in cancer therapy and provides promising avenues for future treatments." (PMID 40873633, 2025). "Moreover, drug sensitivity assays revealed that high EMC2 expression sensitized tumor cells to PDK1/AKT inhibition." (PMID 40303285, 2025). "PDK1 plays a major role in glycolysis and is closely related to tumor metabolism reprogramming." (PMID 40971960, 2025).
tumor (continued). "Second, tumor subsets enriched for microenvironment features, including hypoxia markers (e.g., Slc2a1, Pdk1, Car9), extracellular matrix (ECM) genes (e.g., Matn2, Fn1, Dcn, Col6a1), vasculature (e.g., Cdh5, Pecam1, Vwf), and interferon response genes (e.g., Rsad2, Ifit3, Gbp3, Cxcl10, Cd274)." (PMID 40171265, 2025). "Moreover, with its activity on other downstream kinases, PDK1 is capable of driving tumor-promoting effects even outside the said pathways." (PMID 40649898, 2025). "AUF1 further enhances cell invasion and proliferation by concurrently stabilizing the mRNAs associated with epithelial-mesenchymal transition inducer ZEB1 and AKT signaling pathway activator PDK1; its activity can be inhibited by tumor suppressor microRNAs miR-141/146b-5p." (PMID 41019082, 2025). "Additionally, while our findings highlight the potential of PDK1 as a candidate target, they also raise questions regarding its role in the tumor microenvironment." (PMID 40971960, 2025). "Interestingly, we observed that the tumor surface of PDK1-shRNA MCF7 cells was pale and had fewer blood vessels." (PMID 38560503, 2024). "Furthermore, tumor samples treated with BA exhibited an increase in Cav-1 expression and a notable decrease in c-Myc and PDK1 levels in tumor tissues, providing evidence that a dosage of 250 mg/kg BA can effectively suppress glycolytic activity in vivo." (PMID 38563878, 2024). "PDK1 regulation by HIF-1α promotes tumor glycolysis and malignant progression." (PMID 38671369, 2024). "CRISPR-mediated PDK1 knockout effectively inhibited tumor formation in xenograft models." (PMID 38689087, 2024). "Meanwhile, flow cytometry indicated that PDK1 markedly inhibited the apoptosis of tumor cells." (PMID 38560503, 2024). "Additionally, mouse models were established using human Skov3 cells, which cannot reflect the impact of the tumor microenvironment on PDK1 or BGN during EOC progression." (PMID 39578715, 2024). "In addition, a subcutaneous tumor model in nude mice was established, and the tumorigenesis function of PDK1 was verified." (PMID 38560503, 2024). "It has been reported that significantly downregulated miR-379 in OS tissues and cell lines (MG-63, U2OS, SOSP-9607, SAOS-2) can significantly upregulate PDK1 expression, and high expression of PDK1 promotes tumour cell proliferation and migration, indicating that PDK1 is a direct target of miR-379." (PMID 38288377, 2024). "Pyruvate dehydrogenase kinase 1 (PDK1) was overexpressed in tumors, which could be employed as molecular target to reverse immunosuppression in tumor microenvironment." (PMID 39479443, 2024). "In addition, overexpression of PDK1 reversed the suppressive effect of LINC01419 knockdown on tumour growth in vivo." (PMID 39625183, 2024). "Furthermore,PDK1 knockdown markedly reduced the tumor burden and peritoneal metastasis of Skov3 cells in mice." (PMID 39578715, 2024). "Furthermore, tumor-bearing mouse models are established to assess the impacts of PDK1 and BGN on EOC tumor growth and metastasisin vivo." (PMID 39578715, 2024). "Finally, overexpression of PDK1 appeared less potent than MAPK4 in rescuing the growth of these MAPK4-KO cells/xenografts, which are consistent with the notion that PDK1 only partially mediates MAPK4 tumor-promoting activity." (PMID 37531320, 2023). "Interestingly, neither of the 2 MNK1/2 inhibitors tested (SLV-2436 and eFT508) exhibited notable activity in inhibiting MAPK4-induced PDK1 protein expression or tumor cell growth." (PMID 37531320, 2023). "Together, these data suggest that PDK1 may only partially mediate MAPK4 activities in promoting tumor cell growth and resistance to PI3K blockade." (PMID 37531320, 2023). "Besides phosphorylating/activating AKT at the cell membrane in a PI3K-dependent manner, PDK1 also exhibits constitutive activity on many other AGC kinases for tumor-promoting activity." (PMID 37531320, 2023). "Accordingly, co-blockade of AKT and PDK1 largely blocks MAPK4 tumor-promoting activity." (PMID 37531320, 2023).